FSHR (follicle stimulating hormone receptor)
Diseases named in the same sentence as FSHR in open-access papers (continued):
Sharing a sentence is not in itself a finding about the gene and the disease.
Infertility (continued). "In contrast to these studies, several researches have indicated a correlation between FSHR polymorphisms and azoospermia or infertility." (PMID 26730241, 2015). "Knowledge of combination of SNPs in FSH beta and FSHR is essential for determining patient risk/treatment outcome and for designing treatment in cases of infertility." (PMID 26236283, 2015). "A pilot pharmacogenetic study has shown that only the infertile male patients carrying Ser-allele of the FSHR Asn680Ser polymorphism showed significant increase in total sperm count, concentration, motility and percentage of normal morphology forms." (PMID 23413141, 2013). "In females, FSHR is required for ovarian and follicular development and loss of FSHR causes infertility." (PMID 24205076, 2013). "Mice carrying mutated FSHR gene, the so-called FORKO (follitropin receptor knockout) mouse, is an appropriate animal model for studying human hypergonadotropic ovarian dysgenesis and infertility." (PMID 22412875, 2012). "FSHR inactivating mutations may cause amenorrhea, infertility, and premature ovarian failure, whereas activating mutations can predispose to ovarian hyperstimulation syndrome, implying the importance of the FSHR function in female reproduction." (PMID 38987655, 2024). "Splicing variants or SNPs in FSHR gene were found to have little impact on infertility." (PMID 37504264, 2023). "Furthermore, the FSHR rs6165 GG, rs6165 AA, ESR1 rs9340799 GA, and rs2234693 TC gene combination enhanced the protective effect of FSHR gene variants and was associated with a reduced risk of fibrocystic mastopathy in infertile women." (PMID 37239044, 2023). "However, when we analyzed the frequencies of the SNP in FSHR (rs6166) among POSEIDON groups, our current study indicated a higher frequency of A allele of FSHR (rs6166) in the women with infertility with adequate ovarian reserve (POSEIDON group 1 and 2)." (PMID 36769444, 2023). "Studies reporting various mutations, polymorphisms, and alternatively spliced variants of FSHR have correlated these products with their respective phenotypes, clearly suggesting that such genetic alterations may result in infertility." (PMID 35002517, 2022). "In addition, the complete inactivation of the FSHR in women causes infertility with a paradoxical abundance of small follicles, whose density is close to that of the prepubertal ovaries, with a large number of reserve follicles." (PMID 34884539, 2021). "Many FSHR associated treatments like synthetic or natural derived follicle-stimulating medicines, gonadotropins, and ovarian stimulation drugs such as clomiphene and metformin are used for infertility treatment in females." (PMID 33561079, 2021). "However, all together, the genetics of FSH responsiveness in infertility treatment can rest not only on potential alterations of the FSHR gene via mutations or polymorphisms but also on a host of other core genes for intracellular signaling pathways too." (PMID 33561079, 2021). "Although such mutations may rarely occur in infertile women, they can induce an impaired signaling pathway in a highly complex process of FSHR inducing molecular trafficking." (PMID 33561079, 2021). "Given the significant role of FSH in fertility, genetic abnormalities of the FSHR could cause infertility." (PMID 28764642, 2017). "The controversy in the previously published studies regarding the relationship between FSHR polymorphisms and fertility showed that several factors, such as ethnicity or the cause of infertility, might have affected the results." (PMID 26730241, 2015). "Thus, the present study aimed to investigate the correlation between FSHR gene polymorphism (A919G and A2039G) and susceptibility to azoospermia in a group of Iranian infertile men from Fars province (Iran) in comparison to a healthy control group." (PMID 26730241, 2015).
Infertility (continued). "Thus, in a population of infertile women, FSHR gene polymorphism at position 680 is associated with the ovarian response to the controlled ovary hyperstimulation( COH)." (PMID 24167601, 2013). "However, it is already clear that the relationship of FSHR Ser680/Ser680 variant polymorphism to lower fecundity can have clinical relevance; e.g. more conservative infertility management can be suggested for women with unexplained infertility whose have this genetic variation." (PMID 29954364, 2018). "FSHR inactivating mutations may cause primary or secondary amenorrhea, infertility, and premature ovarian failure; whereas activating mutations can predispose to ovarian hyperstimulation syndrome, as a consequence of exogenous FSH administration, or to a spontaneous onset." (PMID 29954364, 2018). "In the genotyped cohort, the FSHR N680S genotype distribution was similar to that in other Caucasian infertility cohorts." (PMID 40433406, 2025). "The Suzuki-Miyaura coupling of 18 and N-methylpyrrole-2-boronic acid pinacol ester provided the corresponding product 62 in 93% yield, which contains the core skeleton of a follicle-stimulating hormone receptor agonists used for treating infertility." (PMID 40815636, 2025). "A future attempt should be made to study extensively the polymorphisms of the FSHR gene and to correlate them with CART and leptin gene expression and with the hormonal profile of obese women suffering from infertility." (PMID 38673534, 2024). "Second, we compared the distribution of LIF (rs929271) and FSHR (rs6166) in patients with infertility with an adequate ovarian reserve (POSEIDON group 1 and 2) with normal responders." (PMID 36769444, 2023). "In the case of FSHR, the inactivating mutations can cause primary or secondary amenorrhea, premature ovarian failure (POF), and even infertility, while activating mutations can result in OHSS42." (PMID 36720854, 2023). "The older women with infertility (age ≥ 35 years; POSEIDON group 2) were associated with a higher A allele frequency of FSHR (rs6166)." (PMID 36769444, 2023). "Researchers also identified a statistically significant positive correlation between the expression of FSHR in endometriosis glands and the duration of infertility (p = 0.0005) and the rectovaginal nodule size (p = 0.002)." (PMID 37174718, 2023). "As far as we know, this is the first study evaluating the association between FSHR rs6166 and ESR1 rs2234693 polymorphisms and PCOS in the Portuguese population with infertility." (PMID 37012960, 2023). "The small molecule agonist of FSHR has been considered as potential oral replacement of protein hormone for infertility treatment." (PMID 36720854, 2023). "More investigations on novel drugs are needed for increasing the expression level of FSHR thus improving fecundity in infertile women with OMA." (PMID 35884788, 2022). "Two of the proteins stably interacting specifically with A189V FSHR, amyloid precursor protein (APP) and TGF-beta receptor type-1 (TGFBR1), have been indicated to have a role in gonadal development or linked to infertility." (PMID 35471239, 2022). "Follicle-stimulating hormone receptor (FSHR) plays an essential role as one of the most important molecules in response to some of infertility related medications." (PMID 33561079, 2021). "Such scenarios cause a specific type of challenges, as most of the sequencing approaches are designed for SNV detection in FSHR and other related infertility genes in the clinical practice." (PMID 33561079, 2021). "Through 40 fully scrutinized publications in this review, 25 of them showed the relevant impact of FSHR genotype on infertility treatment outcomes in the clinic." (PMID 33561079, 2021). "Yet, to avoid any misdiagnosis and/or mismanagement of impaired ovarian response patients, genetic profiling of FSHR should be taken into account in clinical infertility centers too." (PMID 33561079, 2021).
Infertility (continued). "These alleles are considered the variations with PGx effects in the FSHR gene during infertility treatment approaches, and the consistent data for retrieved oocytes, stimulation duration, FSH consumption, etc., are provided for them adequately." (PMID 33561079, 2021). "A recent case–control study evaluated three FSHR SNPs (c.919A > G, c.2039A > G, and c.−29G > A) in 255 infertile men and 340 healthy controls." (PMID 32260182, 2020). "Our structure-activity guided drug discovery, combined with preclinical monitoring of thyroid stimulating hormone receptor (TSHR) activity, allowed us to develop novel FSHR-AA suitable for use in future human infertility treatments." (PMID 33519465, 2020). "Female mice with FSHβ or FSHR gene knockout present an incomplete follicle development leading to infertility, whereas males display oligozoospermia and subfertility." (PMID 30930853, 2019). "None of the COS response parameters were significantly different among groups of donors (p = 0.711) and infertile patients (p = 0.964) carrying any of the three genotypes (GG, GA or AA) at position − 29 of the FSHR." (PMID 30340493, 2018). "The frequency of the GG genotype at position c.2039 of the FSHR in Mexican mestizo subjects is among the lowest reported in the literature for both normal and infertile women." (PMID 30340493, 2018). "In the present study, we included 340 fertile males and 255 infertile males, consisting of 166 with azoospermia or severe oligozoospermia, and 89 with oligospermia, and we investigated the association between FSHB, FSHR gene polymorphisms and male infertility." (PMID 28764642, 2017). "The population-based Baltic male cohort (Estonians, Latvians, Lithuanians; n = 1052) and Estonian oligo-/azoospermic (sperm concentration <20 × 106/mL) idiopathic infertile patients (n = 738) were genotyped for the FSHR Asn680Ser using PCR-RFLP." (PMID 23413141, 2013). "Majority of reports represent case-control studies comparing the distribution of alternative FSHR isoforms (Thr307-Asn680, Ala307-Ser680) in groups of infertile men vs. fertile controls." (PMID 23413141, 2013). "In men, low fertility with a quantitative reduction in spermatogenesis occurs without FSHR function, while mutations in the FSHβ subunit can lead to azoospermia and infertility." (PMID 39140811, 2024). "Basic demographic characteristics, such as age, BMI (body mass index), and causeand duration of infertility, were not significantly different between women withdifferent FSHR Ala307Thr (rs6165) genotypes." (PMID 36995260, 2023). "Thereafter, we could consider genotyping LIF (rs929271) and FSHR (rs6166) among young and older women with infertility who are expected to be normal responders before they enter their first ART to avoid an unexpected or a hypo-response." (PMID 36769444, 2023). "With regard to the clinical implications of our findings, LIF (rs929271) and FSHR (rs6166) analysis should be considered for young and older women with infertility who are expected to be normal responders but who exhibit an unexpectedly poor or suboptimal COH response." (PMID 36769444, 2023). "Both mutations and SNPs in FSHR have been shown to impair FSH signaling, resulting in infertility." (PMID 37504264, 2023). "Main characteristics of infertile women, according to their FSHR geneAla307Thr (rs6165) genotype." (PMID 36995260, 2023). "This suggests that FSHR (rs6166) may lead to lower numbers of mature oocytes in older women with infertility (age ≥ 35 years) undergoing ART treatment." (PMID 36769444, 2023). "In men, inactivating mutations in FSHR lead to subfertility due to oligozoospermia, but not to complete infertility." (PMID 35471239, 2022). "Successful IVM of oocytes was found in a primary infertility patient who carried compound heterozygous FSHR variants and had no response to FSH stimulation." (PMID 36704038, 2022). "] reported FSHR isoforms in infertile men in an infertility clinic." (PMID 34717708, 2021).
Infertility (continued). "The combinations of p.N680S and other FSHR SNPs are linked to individual-specific pathophysiological effects, opening perspectives for a new pharmacological approach, optimizing the pharmacogenetic potential of FSH for infertility treatments." (PMID 32218314, 2020). "Among the FSHR allosteric modulators evaluated to date, none had combined sufficient potency as FSHR agonists, oral bioavailability or adequate safety profiles suitable for human infertility treatments (reviewed)." (PMID 33519465, 2020). "Only one study, carried out in 105 infertile patients, has assessed the role of the FSHR c." (PMID 32498268, 2020). "Consistently, women expressing non-functional variants of the FSHR are infertile while men are oligozoospermic, yet fertile." (PMID 30930853, 2019). "Moreover, the reduced level of granulosa cell FSHR expression in IGF-I knockout ovaries led to the infertility in the female." (PMID 28969048, 2017). "There are several studies regarding FSHR SNPs and its relationship with infertility." (PMID 26730241, 2015). "Genotyping the FSHR N680S together with some additional markers may provide a means of identifying a group of poor responders before infertility treatment is initiated." (PMID 25526787, 2014). "Primary ovarian failure is characterized by amenorrhea and infertility in a normal karyotype female, with an elevated serum level of follicle-stimulating hormone (FSH) and a decrease level of estrogen caused by a mutation in FSH receptor (FSHR) gene." (PMID 22412875, 2012). "However, for women with infertility with low ovarian reserve, the frequency of A allele of FSHR (rs6166) was not distributed differently." (PMID 36769444, 2023). "Together, our analysis indicated that H6157.42 in FSHR played essential roles in determining FSHR ligand selectivity and provided new insights for designing more specific small molecular agonists targeting this important receptor for infertility and in vitro fertilization." (PMID 36720854, 2023). "Together, our structures provide a molecular basis of FSH and small allosteric agonist-mediated FSHR activation, which could inspire the design of FSHR-targeted drugs for the treatment of infertility and controlled ovarian stimulation for in vitro fertilization." (PMID 36720854, 2023). "The FSHR (follicle-stimulating hormone receptor) gene also showed polymorphisms in PCOS women: interestingly, the two detected missense mutations, p.Ala307Thr and p.Asn680Ser, negatively affect ovarian FSH response, causing an impaired oocyte maturation, anovulation and consequent infertility." (PMID 35740328, 2022). "However, the consideration of such alleles during FSHR genotyping in women with diverse responses to infertility drugs will not be useless." (PMID 33561079, 2021). "Mutations and SNPs in FSH/FSHR have been studied extensively to investigate their role in various biological processes (OHSS, dose of FSH to stimulate the ovaries in an ART clinic etc.)as well as in pathologies (PCOS, POI, infertility, endometriosis, fibroids, reproductive tissue cancers etc.)." (PMID 34717708, 2021). "We set forward to bring conclusive evidence to the effect of FSHR -29G/A in men in analysing a large study group (n = 1,623) comprising of Baltic young male cohort (n = 982) in comparison with Estonian oligozoospermic idiopathic infertile male patients (n = 641)." (PMID 24718625, 2014). "Indeed, infertile patients with serum FSH levels within the normal range may have a “clinical FSH deficiency” resulting from reduced activity of this hormone, which may depend on its glycosylation, FSHR polymorphisms, and other genetic variants." (PMID 39407726, 2024). "LIF (rs929271) and FSHR (rs6166) should be considered as potential biomarkers for poor or suboptimal COH responses among young and older women with infertility who are expected to be normal responders." (PMID 36769444, 2023).
Infertility (continued). "Based on this model, the suppressed expression of follicle-stimulating hormone receptor (FSHR) and reduced litter size were found in OMA mice compared with control, indicating that infertility was impaired in OMA mice." (PMID 35884788, 2022). "Overall, in both study groups the carrier status of FSHR haplotypes exhibited a significant effect on serum FSH (haplotype omnibus test: Baltic cohort, P = 0.007; Estonian oligozoospermic infertile patients, P = 0.045), and total testes volume (P<0.03)." (PMID 24718625, 2014). "Notably, although the genetic composition in young male cohort and oligozoospermic patient group was similar, neither FSHR -29G/A alone nor FSHR variants formed from the combinations of -29G/A and Asn680Ser appeared to significantly modulate reproductive physiology among infertility patients." (PMID 24718625, 2014). "Follicular stimulating hormone (FSH) is a glycoprotein and widely used for the treatment of infertility; FSH action is mediated by FSH receptor (FSHR), SNPs of which determine the ovarian response." (PMID 24167601, 2013). "No statistical difference was observed in FSHR rs6166 allele and genotype frequencies when comparing the Baltic cohort with Estonian infertility patients, as well as among the oligo- and azoospermia subgroups of infertile men (Fisher's exact test, P-value >0.70)." (PMID 23413141, 2013). "To date, more than 30 inactivating mutations of FSHR with demonstrated phenotypes in women have been discovered, most of which have been confirmed to undermine FSH receptor functions by in vitro assays, and there were 16 cases (cases 26–41) who received COS for infertility management." (PMID 40171200, 2025). "The lack of other family history details in women with FI apart from infertility, not documenting consanguinity details, and screening the single SNPs in the FSHR and RNLS genes were the limitations of this study." (PMID 37504264, 2023). "FSHr antibodies have been shown to inhibit the differentiation of spermatogonia to primary spermatocytes, resulting in infertility without a pathological effect on reproductive organs." (PMID 37508065, 2023). "As a contraceptive vaccine, FSHr antibodies have been shown to inhibit the differentiation of spermatogonia to primary spermatocytes, resulting in induced infertility without pathological effects on reproductive organs." (PMID 37508065, 2023). "In the future, pharmacogenomics of FSHR and FSHB as well as innovative compounds may be considered to develop new therapeutic strategies in the management of infertility." (PMID 35349114, 2022). "Inactivating mutations in a number of these GPCRs have been shown to result in intracellular retention and infertility, including the LH receptor (LHCGR/LHR), FSH receptor (FSHR), and GnRHR, with all three being amenable to pharmacological chaperone rescue and restoration of signalling." (PMID 35562976, 2022). "Among the Estonian oligozoospermic infertility patients, none of the four FSHR haplotypes appeared to systematically modulate their reproductive physiology." (PMID 24718625, 2014). "This position is critical as it may be involved in the hormone-binding ability of FSHR and FSH-mediated signal transduction in the infertile women undergoing ovarian stimulation." (PMID 24167601, 2013). "To date, no study has evaluated the effect of an FSH switching protocol in infertile patients, so it is not known whether this condition can be ascribed to the habituation of the FSHR to the specific FSH preparation used." (PMID 39407726, 2024). "However, the FSHR polymorphisms at the studied sites were shown not to be associated with idiopathic male infertility or to influence FSH levels in both normal and infertile males in the Han-Chinese population." (PMID 29219278, 2018). "Furthermore, FSHR, mapped on chromosome 2 at 2p16, was shown not to be correlated with sperm count in infertile males." (PMID 29219278, 2018).